IL2 (interleukin 2)
Diseases named in the same sentence as IL2 in open-access papers (continued):
Sharing a sentence is not in itself a finding about the gene and the disease.
tumor (continued). "An important number of cytokine levels were below the detection limit of the method (LOD and/or LLOQ) such as IL-2, IL-10, IL-11, IL-12 (p40), IL-12 (p70), IL-19, IL-27 (p28), IL-28A/IFN-λ2, IL-29/IFN-λ1, IFN-α2 and osteocalcin in both tumor and normal tissue control samples." (PMID 33846436, 2021). "In vitro studies showed anti-NKG2A Monalizumab treatment prompts increased CD107a expression, a marker for activated NK cells, and IFN-γ production by IL-2 activated NK cells and CD8+ T cells, yielding significant improvements in tumor growth control and prognosis." (PMID 33995422, 2021). "In summary, low glucose concentrations, as found in BM of MM patients, by itself did not compromise the anti-tumor potential of IL-2 activated NK cells in vitro." (PMID 34094908, 2021). "While long-term T cell culture in IL-2 drives terminal differentiation, the common γ-chain cytokines IL-7 and IL-15 have been reported to promote a central memory T cell (TCM cell) phenotype enabling superior persistence and in vivo tumor control upon ACT." (PMID 33156338, 2021). "Compared to traditional IL-2, NKTR-214 does not cause significant amplification of CD4+ Foxp3+ Tregs, and thus, has greater anti-tumor activity and fewer adverse effects." (PMID 33746989, 2021). "Similar to Tregs, myeloid-derived suppressor cells (MDSC) do not have a direct anti-tumor effect, but they reduce arginine amino acid, nitric oxide synthase and interleukin-2 (IL-2) levels by expressing arginine I in effector T cells." (PMID 34205019, 2021). "Thus, adding both ASA and low-dose IL-2 to the OCDC-Bev-Cy combinatorial regimen significantly increased total and perforin-expressing CD3+ and CD8+ TILs infiltrations while reducing tumor-infiltrating Treg cells." (PMID 33723260, 2021). "5-FU alone can only promote the expression of IFN-γ and TNF-α in tumor-bearing mice but demonstrated no evident effect on IL-2." (PMID 34803677, 2021). "Interestingly, expression of the marker gene BAMBI, a TGF-β pseudoreceptor involved in EMT and constitutive IL2/STAT5 signalling, has previously been correlated with tumour growth, tumour invasion and carboplatin resistance in HGSTOC." (PMID 34238352, 2021). "Testing combinations of various cytokines in T cell culture media revealed that tumor antigen specific CD4+ T cell growth was improved by culturing in IL-1β, IL-2, IL-6, IL-7, IL-15, IL-21, IL-23, and TGFβ, and that the addition of TGFβ was critical for the improved performance of the cocktail." (PMID 33362774, 2020). "It is noteworthy to emphasize that, compared to naive nontreated NK cells, a short-term treatment with HSP70/IL-2-activated NK-cells results in significant tumor shrinkage and survival." (PMID 32218162, 2020). "However, when comparing the effect of CM and physical co-culture of the tumor cells with modified hADSCs, the proliferation of SH-SY5Y cells was significantly decreased (over 20%) after co-culture with hADSCs-IL2 on plastic compared with control co-cultures." (PMID 32560387, 2020). "In H22 tumor-bearing mice, oral administration of CSP resulted in increased body weights; peripheral white blood cell counts; thymus and spleen indices; and serum IL-2, IL-6, and TNF-α levels in vivo." (PMID 32595757, 2020). "Indeed, tumor cells infected with EphA2-TEA-VV induced T cell activation, as evidenced by interferon-γ and interleukin-2 secretion." (PMID 32664210, 2020). "MPE-resident CD8+ T cells were co-cultured with autologous monocyte or tumor containing non-hematopoietic cells after 24-h incubation in IL-2 or IL-2 plus anti-CD3/CD28 activating microbeads." (PMID 32867034, 2020).
tumor (continued). "Others have described modulation of cytokine production of IL-1α, IL-1β, IL-2, IL-4, IL-6, IL-8, IL-10, IL-17A, TNF-α, and IFN-γ on tumor cells treated with conventional PDT, but their increase or decrease seems to highly depend on the cell line and PDT protocol used." (PMID 32326519, 2020). "In the absence of a TCR stimulus, only IL-2/IL-12/IL-18- treated γδ T cells exerted a clear and lasting anti-tumor effect, even at a low E:T ratio, i.e., of 0.5:1." (PMID 31947966, 2020). "Compared with the model control group, YPF increased the expression of IL-12, TNF-α, and IFN-γ in tumor and adjacent tissues (p < 0.05 and p < 0.01) but did not affect IL-2 level (p > 0.05)." (PMID 32351590, 2020). "In vivo somatic GM-CSF, IL-2, and HSVtk combination gene therapy had also developed anti-tumor immunity against non-immunogenic mammary carcinoma." (PMID 33329567, 2020). "It has previously been shown that Nr2f6−/− T cells are hyper-reactive in regard of cytokine production (IL-2, IFNγ, TNFα) as those cytokines are direct target genes of NR2F6-dependent transcriptional repression leading to an improved anti-tumor immune contexture at the tumor site." (PMID 31937317, 2020). "Suppressive immune cells in the TME often preferably express pro-tumor Th2 secreted cytokines, such as IL-4 and IL-13, rather than anti-tumor Th1 (e.g., IL-2 production), or secreted cytokines like IFN-γ and tumor necrosis factor-β (TNF-β)." (PMID 32843053, 2020). "Blood tests revealed no elevated tumor markers, with the exception of a mildly elevated interleukin-2." (PMID 32844588, 2020). "Efficient tumor-lytic activity after pharmacologic Vδ2 TCR-stimulation correlates with granzyme B and IFN-γ/TNF-α production in γδ T cells, parameters which we and others found to be enhanced when IL-2, IL-12, and IL-18 are added." (PMID 31947966, 2020). "With regard to SH-SY5Y, TCR-stimulated γδ T cells showed no significant tumor growth inhibition even at a high E:T ratio of 5:1 except when combined with IL-2/IL-12/IL-18." (PMID 31947966, 2020). "In addition, the levels of IFN-γ+-producing CD4+ or CD8+ T cells in splenocytes in vitro and IL-2 and IFN-γ in tumor tissues increased in the DTSP group." (PMID 32903495, 2020). "Among the cytokines we analyzed in these settings, GM-CSF protein expression was partially decreased by IL-2 neutralization in the tumor, but not in dLNs (data not shown)." (PMID 31924474, 2020). "Tumor-infiltrating Trp1 Th-ctx cells expressed high levels of IL-2, with neither αIL-2 nor αIL-7 treatment impacting its expression." (PMID 31924474, 2020). "In patients with resistance (i.e., progressive disease) to systemic PD-L1 checkpoint inhibitor monotherapy, subsequent intralesional IL2 therapy was able to induce a CR in 33% of patients with a potent increase in CD4+ and CD8+ cells from the tumor microenvironment infiltrate." (PMID 32455916, 2020). "At day 14, IL-2 preferentially expanded NK, while NKTR-214 expanded dramatically the T cell compartment, suggesting that the T cells are the main contributors in the enhanced anti-tumor response by NKTR-214 in this model." (PMID 32005809, 2020). "In addition, it is postulated to simultaneously increase the expression of CX3CL1 and other cytokines that enhance the immune response, e.g., IL-2, which significantly increases the effect of CX3CL1 in a tumor." (PMID 32466280, 2020). "Purified ILCs from non-affected colon, tumor border and central tumor tissue were cultured in the presence of IL-2 plus IL-1β and IL-18 for 7−9 days and the resulting expression of HLA-DR and T-cell co-stimulatory molecules was assessed." (PMID 32341343, 2020). "The stimulation of PBMC with zoledronic acid and IL-2 in the absence of autologous tumor cells induced a significant and selective outgrowth of Vγ9 T cells and PBMC released very low amounts of gal-3." (PMID 32695112, 2020).
tumor (continued). "Furthermore, the cytokines related to tumor growth, EMT, metastasis and drug resistance, such as IL-1B, IL-2, Il-4, IL-6, IL-10, IL-17, KC (GRO), were mainly expressed in mT obese models." (PMID 32411709, 2020). "Previous studies of hu14.18 mAb–IL2 fusion protein and of 131I-3F8 mAb were open to various tumor types including sarcoma and completed in 2005, but no results are publicly available and studies no longer are being conducted." (PMID 32733795, 2020). "IL-2 as the main known mitogen of T cells was the first, but not the only one cytokine tested for cultures of anti-tumour T cells." (PMID 32183246, 2020). "Intravenous injection of IL-2/HSP70-treated NK cells, which targeted GBM cells in the brain, did further confirm the effectiveness of activated NK cells, which exhibited specific homing properties, accumulating in the brain, and reaching the tumor cells." (PMID 32218162, 2020). "Alternatively, well-known agents targeting IFNG, IL2, or TLR9 might be considered as adjuncts in tumor types already demonstrating the T cell-inflamed phenotype." (PMID 33106165, 2020). "For the non-irradiated tumor in β2-AR KO mice, we noted a significant increase in expression of several genes including Cd28, Il2, and Zap70; genes showing the greatest decrease included genes which can inhibit effector function (including Il6 and Il10)." (PMID 32286326, 2020). "Treating tumor-bearing mice with such a mutein expanded both Treg and CD8+ T cells to a lesser extent than memory CD8+ T, compared to the administration of wild-type IL2." (PMID 33216834, 2020). "Also, the properties of NARA1leukin are suitable for the development of bispecific antibodies for targeting tumor antigens and provision of CD122-biased IL-2 signals." (PMID 33353953, 2020). "Similarly, dual-targeted CAR-T cells -CD4+ T cells secreted higher levels of IL-2 in the co-cultures of PD-L1+ tumor cells (e.g. A549, NCI-H292, SKOV3) than that in the co-cultures of HER2+ tumor cells." (PMID 33292688, 2020). "In addition, both MMP2 and TGF-β1 proteins as well as IL6 and IL8, whose secretion levels were high in hADSCs-IL2, are important participants in EMT of tumor cells." (PMID 32560387, 2020). "A study of tumor-bearing mice found that APS could enhance the immune function by increasing the levels of cytokines, such as IL2, IL6, IL12, and TNF-α." (PMID 32265719, 2020). "To test the effects of pemetrexed on increasing the efficacy of ICB therapy in the mouse tumor models, we cocultured mouse LL2 or CT26 cancer cell lines with primary splenocytes derived from the mouse spleen and measured the levels of secreted IL-2 and IFN-γ in the coculture system." (PMID 33243934, 2020). "Radiation and treatment with immunocytokine hu14.18-IL2, a fusion protein linking hu14.18 anti-GD2 mAb and IL2, produced significant anti-tumor response in NXS2 mice, but not in N-MYC driven 9464D-GD2 mice, compared to monotherapy." (PMID 32983125, 2020). "In terms of inflammation, DEX decreased the concentration of IL-2 in plasma of normal mice treated with RT, but not in tumor-bearing mice." (PMID 32325715, 2020). "In order to characterize the M-406/CBi/L model with respect to cytokines involved in the different phases of tumor immunoediting, it was evaluated the concentration of Th-1 (IFN-γ, IL-2) and Th-2 (IL-10, IL-4) cytokines in serum from tumor bearing animals during EL, EQ and ES phases." (PMID 33312693, 2020). "The density of mHsp70 expression plays a crucial role in the recognition of tumor cells by Hsp70-peptide TKD/IL-2-activated NK cells, but not by cytotoxic CD8-positive T lymphocytes, as previously demonstrated." (PMID 32276468, 2020). "MCs also release cytokines such as IL-10, IL-2, IFN-γ which play a direct anti-tumor role." (PMID 32626535, 2020).
tumor (continued). "Transduction using iaIL-12 increased the production of IFN-γ, TNF-α, and IL-2 as compared with transduction using negative control (iGFP) when T cells were cocultured with tumor cells expressing the target antigen (SS4050 and CaSki)." (PMID 31959727, 2020). "Indeed, adoptive transfer of iNKT cells activated in vitro with a combination of IL-12 and IL-18 robustly produces IL-2 and IFN-γ, which in turn activates NK cells to mediate anti-tumor response in vivo." (PMID 32708464, 2020). "Significant tumor reduction and a decrease in the progression rates of the established tumors in the groups injected with Ii-RGC were observed, compared to the groups treated with IL-2 plus empty plasmid controls (p < 0.002)." (PMID 32079263, 2020). "Taken together, this data suggest that disruption of lymphatic Nr2f6 converts tumor-infiltrating T cells into IFNγ- and IL-2-hypersecreting effector cells, apparently sufficient to prime the TIME for immune checkpoint therapy to more effectively control tumor growth." (PMID 31937317, 2020). "Similarly, in an in vivo model of AML, transient depletion of Tregs using IL-2-diphtheria toxin (IL-2DT) resulted in reduced AML tumor burden and improved the proliferation of adoptively-transferred tumor-reactive cytotoxic T-lymphocytes (CTLs)." (PMID 33643299, 2020). "Under the costimulation of secreted IL-2 and exosomal CD80, the expression of exosomal peptide MHC I is passed to CD8+ T cells, thereby stimulating the proliferation of CD8+ T cells and inducing more effective anti-tumor immunity in vivo." (PMID 33183286, 2020). "Intragastric administration of Shiquan-Yuzhen decoction in H22 tumor-bearing mice increased the thymus and spleen indices; upregulated the expression of CD3, CD4, CD8, and TNF-α receptors in lymphocytes; and decreased the expression of IL-2 and IFN-β." (PMID 32595757, 2020). "However, IL-2 immunotherapy damages IL-2 receptor (IL-2R)-positive endothelial cells and stimulates IL-2Rα (CD25)-expressing lymphocytes that curtail anti-tumor responses." (PMID 33353953, 2020). "In order to break tumor resistance towards traditional treatments, we investigate the response of tumor and immune cells to a novel, cytokine-armed oncolytic adenovirus: Ad5/3-d24-E2F-hTNFa-IRES-hIL2 (also known as TILT-123 and OAd.TNFa-IL2)." (PMID 32225009, 2020). "In another study, the cancer-immune dynamics resulting from interleukin-2 (IL-2) or adoptive cell transfer (ACT) immunotherapy was described, suggesting that a small increase in antigenicity led to significant variations in tumor size." (PMID 30871264, 2019). "Because CD8POS T cells are critical to mediate tumor cell killing, we first evaluated the expression of PD-1 and PD-L1 on CD8POS T cells, present within the pool of PBMCs, stimulated with a cocktail of anti-CD3 antibodies and IL-2." (PMID 31234464, 2019). "In addition, PEGylated IL-2 (also known as NKTR-214) that binds CD122 (IL-2Rβ), expressed by both T and NK cells, is able to boost preferentially these cells and their anti-tumor responses." (PMID 32010130, 2019). "However, there were no observable increases in the expression of the proinflammatory cytokines tested (IL-2, TNF-α, and IFNγ) within the tumor tissues." (PMID 30979375, 2019). "IL-2 induces the activation of lymphocytes and their differentiation into lymphokine-activated killer (LAK) cells which can recognize and eliminate various tumor cells." (PMID 30693030, 2019). "Notably, nLGs continuously released IL-2 and TGF-β inhibitors into the tumor microenvironment, improved the activity of NK cells and CD8+ T cells, and thereby enhanced anti-tumor immune responses." (PMID 31779642, 2019). "Of note, the IL2 cytokine and the IL2-modified version have been described as being able to synergize with anti-CTLA4 and anti-PD1/PDL-1 antibodies in terms of tumor control, but only a combination of the IL2-based cytokine with CTLA4 is able to re-activate NK cells in vivo." (PMID 31614774, 2019).
tumor (continued). "Williams and colleagues reported that cancer patients who received tumors admixed with IL-2 had an average 33% higher serum titer against autologous tumor cells whereas only an 8% increase was seen in the non-IL-2 injected patients." (PMID 31289297, 2019). "After antigen recognition, activation, and proliferation, CD4+ cells synthesize and secrete interleukin-2 (IL-2), human interferon-C (IFN-C), and tumor necrosis factor (TNF), which can dissolve and directly kill tumor cells by recognizing and binding antigens on tumors through antigen receptors." (PMID 31781277, 2019). "Accordingly, the survival at day 100 post-inoculum of tumor cells was 61% for mice in this group as compared to 15% in RES group and 13% in IL-2 group, suggesting that the immunomodulatory effects of RES are dose-dependent and that polyphenols in general can elicit strong chemo-supportive effects." (PMID 30959898, 2019). "Another potential explanation for the lack of efficacy of IL-2 treatment is the expansion of regulatory T cell (Treg) that will interfere with the generation of anti-tumor responses." (PMID 31340613, 2019). "Then, MHC-matched DCs were incubated with 500 μg/mL MA and/or 300 μg/mL LAM and were co-cultured with MMC-treated T24 cells overnight at 37 °C before being further co-cultured with MHC-matched naïve CD3+ T cells MA for an additional 2 weeks in the presence of IL-2 and MMC-treated T24 tumor cells." (PMID 31531696, 2019). "The in vivo mechanism(s) by which these MHC class I-restricted CD4+ T cells mediate anti-tumor effects could be further investigated by in vivo blockade of IFN-γ, TNF-α or IL-2, or by using IFN-γR or TNF-αR knockdown cancer cells." (PMID 30626427, 2019). "As low-dose IL-2 can activate Treg, current efforts are testing constructs that selectively bind to NK cells to support anti-tumor immunity without driving Treg proliferation." (PMID 31456796, 2019). "Their results indicate that IL-2 treatment alone does not boost the immune system enough to clear the tumor." (PMID 31611927, 2019). "Also, the activation of Tumor Necrosis Factor (TNF) family ligands that expressed on the surface of NK cells with IL-2, IL-15, IL-12, IL-18, and CD40 cytokines production induce NK cell cytotoxicity against tumor target cells and IFNγ production." (PMID 31457012, 2019). "Removal of the E.G7 cancer cells did not impact the reduced IL-2 production by the T cells when compared to levels secreted from T cells activated by DC in the absence of the tumor cells." (PMID 31602007, 2019). "Therefore, we mainly tested the anti-tumor effects of four representative agents in HMSM, including anti-WNT5A antibody, PLX3997, Anti-IL-2 antibody (IL-2 neutralization), and EGFR inhibitor." (PMID 31504033, 2019). "Interestingly, the IL-2/S-15/Akti-expanded Tils and demonstrated superior functional tumor recognition, as indicated by higher IFN-γ production levels than the Tils expanded by IL-2/S-15 and IL-2/Akti." (PMID 31827396, 2019). "NKTR-214 is an investigational, first-in-class, CD122 preferential agonist that functions as a pegylated recombinant interleukin-2 (IL-2) with cellular effects in activation of CD8+ T and natural killer (NK) cells without unwanted expansion of T regulatory (Treg) cells in the tumor microenvironment." (PMID 31484560, 2019). "sPD-1(soluble PD-1), interacting with PD-L1, could prevent PD-1 from binding with PD-L1 and promote effective tumor immunity, possibly resulting from decreased IL-10, TGF-β and increased IL-2 TNF-α and IFN-γ." (PMID 31708918, 2019). "Additionally, CD4 + CD25 + Treg cells secrete TGF-β and IL-10 to suppress effector T cells such as CD8 + cytotoxic T lymphocytes infiltrating the tumor into HCC secreting anti-tumor effector molecules such as IFN -γ, IL-2 and TNFα." (PMID 31600917, 2019). "Additionally, IL-15 is able to reverse tumor-tolerant CD8+ T cells, when IL-2 and IL-7 were unable to, restoring antigen responsiveness and leading to tumor clearance." (PMID 30842774, 2019).